SOX2 (SRY-box transcription factor 2)
Diseases named in the same sentence as SOX2 in open-access papers (continued):
Sharing a sentence is not in itself a finding about the gene and the disease.
glioma (continued). "In murine PDGFB-induced glioma cultures and primary human GBM cultures stroma-derived osteopontin was responsible for up-regulation of NANOG, SOX2, OCT4, and ID1 expression." (PMID 28030801, 2017). "The expression of glioma stem cell marker CD133 was reduced after single or combined treatments with NOTCH inhibitors, whereas the triple combination also decreased SOX2 and Nestin expression." (PMID 27183910, 2016). "Our observations sustain the central role of Oct4 as described in glioma cells and suggest that the cellular mechanism occurring during the retinal regeneration in zebrafish (re-induction of pluripotency factors like Oct4 or Sox2 in Müller glia) could be partially conserved in mammalian CNS." (PMID 26381429, 2016). "Our results from the analysis of tumor tissues from patients with malignant gliomas have demonstrated preferential expression of IL-17R in glioma cells which also expressed GSC markers CD133, Nestin, and Sox2." (PMID 26755664, 2016). "The regulation of SOX2 by SHH occurs in neural and brain stem cells, and the pharmacological inhibition of these pathways silences SOX2 expression and impairs glioma cells’ tumorigenic activity." (PMID 27822457, 2016). "In human glioma cells, SOX21 overexpression inhibits SOX2 expression and induces apoptosis because of the interaction between SOX21 and SOX2." (PMID 27933111, 2016). "Flow cytometric analysis also confirmed co-expression of IL-17R and the transcription factor Sox-2, along with CD133 in patient-derived glioma cells." (PMID 26755664, 2016). "We found that the glioma stem cell marker CD133, SOX2 and Nestin were reduced following combination treatments and NOTCH inhibitors albeit in a different manner." (PMID 27183910, 2016). "To search for a relationship of these data with the diminution of undifferentiated cells, we have evaluated the expression levels of the main markers for glioma stem cells (GSC), AC133, Sox2 and Oct4." (PMID 27385098, 2016). "In agreement with this last function, SOX2 is one of the transcription factors, together with POU3F2, OLIG2, and SALL2, which is sufficient to reprogram differentiated glioma cells into induced GSCs, similar to GSCs obtained from human biopsies." (PMID 27822457, 2016). "The expressions of SOX2, OCT4 and NANOG correlate positively with the pathological grade of gliomas." (PMID 27225481, 2016). "Current research demonstrates a positive correlation between the expression of SOX2, OCT4, and NANOG and the pathological grade of gliomas." (PMID 26258069, 2015). "The STEAM panel consisted of sex determining region Y-box 2 (SOX2), tubulin beta-3, EGFR, A2B5, and c-Met and found specifically on high-grade glioma cells." (PMID 26322014, 2015). "The amplified expression levels of SOX2, OCT4, and NANOG transcription factors in grade IV gliomas implicate a possible clinical intervention." (PMID 26258069, 2015). "Many of these up-regulated TAPPs are common in gliomas and other brain cancers, such as Aim2, EZH2, GP100, Mage-1, MageA4, MageA10, Sart-1, -3, Trp-1, and Sox2." (PMID 26175925, 2015). "It has also been demonstrated that ID4 protein activates SRY (sex determining region Y)-box 2 (SOX2) transcription in GBM and glioma stem cells." (PMID 23613880, 2013). "Western blot analysis of these cell lines demonstrated a decrease in SOX2 expression upon addition of LNA-miR-21, which confirms the data obtained from the mouse glioma cell lines." (PMID 22931209, 2012). "The glioma stem cells obtained from CD133+ cells demonstrated increased expression of Twist1 and Sox2 accompanied by significant increase in the mesenchymal markers such as N-cadherin, vimentin and β-catenin." (PMID 22184289, 2011). "In glioma CSC (GCSC), the expression of some neural stem markers, such as SOX2 and Musashi-1, has been reported." (PMID 21600039, 2011).
glioma (continued). "Further investigations using the SOX2-depleted glioblastoma cells and primary GBM cell preparations, respectively, are warranted which should give further insights of the role of SOX2 in glioma cell biology." (PMID 22070920, 2011). "NOTCH1, SOX2, TJP1/ZO1, ZEB1, and ZEB2 have higher expression in lower-grade glioma vs GBM." (PMID 40679044, 2025). "However, in glioma stem-like cells, it was found that METTL3 expression increased, promoting sex determining region Y-box 2 (SOX2) mRNA m6A modification immersion and increased stability, thereby maintaining its stem cell characteristics." (PMID 40356596, 2025). "Moreover, the upregulation of SOX2 mediated by METTL3 and the increased expression of ALKBH5 also enhance the radioresistance of glioma." (PMID 40469294, 2025). "However, high expression of SOX2 can inhibit the function of TET, thus promoting the development of glioma." (PMID 40469294, 2025). "Interestingly, with the addition of four developmental transcription factors (SOX2, OLIG2, SALL2, and POU3F2), differentiated glioma cells can be induced to differentiate into undifferentiated GSCs." (PMID 40469294, 2025). "In glioma stem cells (GSCs), EBF1 expression is inversely correlated with Sox2." (PMID 40508012, 2025). "In GSLCs and glioma tissues, Sohlh1 expression was negatively correlated with the expression of GSLC markers, such as Nestin, CD133, CD44, SOX2 and OCT4, whereas Sohlh1 expression was positively correlated with the expression of GSLC differentiation markers, such as MAP2, GFAP and MBP." (PMID 40418209, 2025). "We confirmed that SOX2 and ZFHX4 can bind to each other in glioma cells by co-immunoprecipitation." (PMID 41458623, 2025). "Interestingly, ALKBH5 can also enhance glioma resistance to TMZ by stimulating the expression of SOX2, which coincides with the role of METTL3 in stabilizing GSCs through the promotion of SOX2 expression." (PMID 40469294, 2025). "Furthermore, SUV39H1 expression was positively correlated with SOX2 and OLIG2 expression in GBM samples from the TCGA and Chinese Glioma Genome Atlas (CGGA) databases." (PMID 40059829, 2025). "Additionally, Shikonin treatments resulted in diminished levels of glioma stem cell markers (SOX2, CD44, CHI3L1, and CD24) and the BMDM-derived TAM marker CD49D in glioma cells and subcutaneous animal models." (PMID 39619148, 2024). "In glioma, recent research demonstrates that the long non-coding RNA PVT1 oncogene enhances stemness and resistance to temozolomide (TMZ) in glioma through the miR-365/ELF4/SRY-Box Transcription Factor 2 (SOX2) pathway." (PMID 39132148, 2024). "We have shown that two of these reprogramming transcription factors, Oct4 and Sox2, are sufficient to induce non-glioma-propagating non-stem-like glioma cells (non-GSCs) to transition to glioma-propagating stem cells (GSCs)." (PMID 39796709, 2024). "Notably, subsequent multiplex histologic studies demonstrated not only the predominant presence of Hsp70 in live glioma tissues but also its colocalization in tumor stem cells (as described by CD133, SOX2, and nestin stemness markers coexpression)." (PMID 39015084, 2024). "Moreover, the overexpression of SOX21 forms a complex with SOX2, altering the balance and composition of SOX2 and SOX21, consequently inducing apoptosis in glioma cells." (PMID 38331879, 2024).
glioma (continued). "The results obtained revealed that MDM2 was more highly expressed in stem cells (expressing the stem cell marker SOX2) than in non-stem cells (not expressing SOX2) in all three pairs of the glioma stem cell line and its non-stem cell counterpart examined." (PMID 38612758, 2024). "Moreover, SOX2 upregulates the expression of lncRNA GSCAR, which competes with miR-6760-5p to upregulate SRSF1 expression, thereby maintaining glioma stem cell (GSC) self-renewal ability." (PMID 38331879, 2024). "Importantly, we found a positive correlation between A3C and glioma stem cell marker genes such as CD133, SOX2, Notch3, CD44, and CXCR4 was noted." (PMID 37809064, 2023). "Furthermore, in some tumors, SOX2 and IE1 can be shown to be expressed within the same glioma cells." (PMID 37058447, 2023). "In glioma, the increased SOX21 expression inhibits SOX2 leading to cancer cell apoptosis." (PMID 38132438, 2023). "Our present data have also revealed that there is a positive relationship between (P)RR and SOX2 expression irrespective of IDH or 1p19q status in glioma patients." (PMID 36646875, 2023). "Furthermore, this regulation of SOX2 on HCMV infection was demonstrated in a neurosphere assay of GSCs and in a murine xenograft model utilizing xenografts from patient-derived glioma tissue." (PMID 37058447, 2023). "Together, these data strongly supported our hypothesis that SOX2 downregulated PML expression to facilitate HCMV infection and viral gene expression, consequently promoting glioma growth." (PMID 37058447, 2023). "Lastly, a positive correlation between SOX2 and IE1 expression in glioma samples could be shown, thus providing clinical evidence that was in agreement with our findings in glioma cells and animal models." (PMID 37058447, 2023). "Compared with the control cells (Ctl), SOX2-OE significantly upregulated UL123 transcription at 4 h post-infection (hpi), UL44 at 12 hpi, and UL99 at 24 hpi, and the corresponding viral protein levels in glioma cell lines and primary GSCs (#286 and #352)." (PMID 37058447, 2023). "Our studies demonstrated that SOX2 downregulated promyelocytic leukemia (PML) and Sp100 and consequently facilitated viral gene expression by decreasing the amount of PML nuclear bodies in HCMV-infected glioma cells." (PMID 37058447, 2023). "Together these studies demonstrated that SOX2 downregulates PML and Sp100 in gliomas." (PMID 37058447, 2023). "In the current study, we demonstrate that elevated SOX2 expression in glioma cells promotes the expression of HCMV proteins, some of which may participate in multiple facets of glioma oncogenesis." (PMID 37058447, 2023). "Lastly, the expression of SOX2 and HCMV immediate early 1 (IE1) protein could be correlated in tissues from glioma patients, and interestingly, elevated levels of SOX2 and IE1 were predictive of a worse clinical outcome." (PMID 37058447, 2023). "We found that PML-NB dots in SOX2-OE cells were much fewer in number and smaller in size than those in Ctl cells, arguing that SOX2-induced downregulation of PML and Sp100 disrupts PML-NBs formation in glioma cells." (PMID 37058447, 2023). "NEAT1 promoted glioma progression via miR-152-3p/CCT6A and miR-132/SOX2 pathway." (PMID 36523600, 2022). "Therefore, we knocked out Sox2 and found that CD133 and CD15 expression decreased significantly and that sphere formation by single glioma cells was decreased." (PMID 34976166, 2022). "Moreover, a more differentiated phenotype is observed in glioma stem-like cells exposed to FN1, with decreased levels of SOX2 and increased levels of GFAP, highlighting the importance of FN1 for glioma onset and progression." (PMID 35562862, 2022). "The molecular mechanism by which SOX2 binds to the CD39 promoter to regulate extracellular ATP levels, and evaluated the immune response enhanced by inhibition of CD39 after ADM treatment in a mouse glioma model." (PMID 35159053, 2022).
glioma (continued). "Thus, the STAT3-dependent (as well as SOX2- and TCF3-dependent) increase in ERRFI1 expression provides the common glioma path for the regulation of EGFR signaling." (PMID 36231068, 2022). "S251 of SOX2 is phosphorylated by DNA-PK under normal conditions, preventing the ubiquitination and degradation of SOX2 mediated by WWP2 and maintaining the stem status of glioma stem cells." (PMID 36091384, 2022). "Additionally, in silico differential analysis of PROM1, SOX2, and NANOG transcript levels was performed on clinical samples from GBM and low-grade glioma (LGG) and compared to healthy tissues as described in the Methods section." (PMID 36497426, 2022). "Undifferentiated (or de-differentiated) glioma stem cells are a unique subset of therapy-resistant cells that express markers of stemness, including CD133+ and neural stem cell markers like nanog, Sox2, and Nestin." (PMID 36316307, 2022). "Paired samples from glioma patients were analyzed by immunohistochemistry for expression of the following stem cell markers: CD133, Musashi, Nanog, Nestin, octamer-binding transcription factor 4 (Oct4), and sex determining region Y-box 2 (Sox2)." (PMID 35183162, 2022). "SOX2 expression has been reported to mark diverse ZIKV target cells including neural progenitor cells, oligodendrocyte precursor cells, astrocytes, and glioma stem cells." (PMID 36174572, 2022). "SOX2 is identified as a downstream target of METTL3, and METTL3 is reported to maintain the expression of SOX2 by facilitating its methylation, thereby leading to the progression of glioma and colorectal cancer." (PMID 35467477, 2022). "The possible interaction between TGF-β (GDNF) and SOXB1 (SOX1, SOX2, SOX3) family members might explain the difficulties in regulating glioma stem cell recurrence after surgical tumor resection and drug resistance." (PMID 35392088, 2022). "In contrast with previous findings, we showed that glioma cells cultured in 3D collagen/FN reacquired stem-like characteristics through the integrin αvβ3/PI3K/AKT cascade, which further induced the downstream transcription factor SOX2 activation." (PMID 33408794, 2021). "Together these in vitro and in silico analyses suggested SOX2 as a top regulator of glioma cell culture gene expression signatures irrespective of growth conditions." (PMID 34021259, 2021). "Similarly, NEAT1 knockdown targets miR-132, which regulates the oncogene sex determining region Y-box protein 2 (SOX2) and miR-107, a modulator of cyclin-dependent kinase 6 (CDK6) and CDK14; these findings were closely connected with glioma malignancy." (PMID 33980320, 2021). "In contrast to glioma stem cells, U87 cells showed no overexpression of stem cell markers, such as SOX2, ZEB1, ATXN1, ALCAM, CD9, ITGA7, CD44 and CHI3L1." (PMID 34680293, 2021). "Stem cell transcription factors (SOX2, OCT4, and NANOG) and ABCA1 are responsive to regulation by CEBPD, which directly binds to the promoter regions of those genes in glioma spheroid cells and TMZ-treated glioma cells." (PMID 33436575, 2021). "In glioma, METTL3 may also promote temozolomide resistance through m6A-mediated stabilization of SOX2, which mediates glioma stem cell formation, as METTL3 knockdown increased temozolomide sensitivity in this context." (PMID 33669361, 2021). "MiR-143, miR-253, miR-452 and miR-145 could down-regulate SOX2 in GBM, whereas miR-145 worked as a tumor-suppressive RNA by targeting SOX9 in human glioma cells." (PMID 32388501, 2020). "Similarly, while stimulation of glioma cells with soluble DLK1 boosted the increase in the expression of the stem cell marker genes NANOG, OCT4, and SOX2 in hypoxic cells, addition of PT2385 blocked this specific DLK1 effect in all cell lines tested." (PMID 33142235, 2020). "Although a specific poly(ADP)ribosylation site was not identified, a physical association of SOX2 and PARP1 has been independently confirmed in murine ESCs and human glioma cells." (PMID 31477842, 2020).
glioma (continued). "MALAT1 promotes the expression of sex determining region Y-box 2 (SOX2), thus boosting the viability and proliferation of glioblastoma stem cells, and it also suppresses apoptosis of glioma cells through reduction of Ras-related protein Rap-1b (Rap1B) levels by removal of miR-101." (PMID 32650527, 2020). "ZDHHC17 over-expression could help maintain glioma cell stemness because the upregulation of the SOX2-positive cell population, whereas MAP2K4 knockdown or genistein treatment suppressed glioma stem cell (GSC) self-renewal." (PMID 31938047, 2020). "Consistent with the role of Sox2 as a transcription factor required for GSC tumorigenicity, we found that TAT-Cx43266–283 strongly decreased GSC tumorigenicity, as judged by the lower number of human glioma cells found 1 month post-implantation." (PMID 31883012, 2020). "We also confirmed that resveratrol obviously inhibited EMT-induced self-renewal ability of glioma stem cells (GSCs) and inhibited EMT-induced cancer stem cell markers Bmi1 and Sox2, suggesting that resveratrol is able to suppress EMT-generated stem cell-like properties in GBM cells." (PMID 31119150, 2019). "Moreover, FABP7 is co-expressed with Sox2 in gliomas and FABP7+/Sox2+ cells are found more abundantly in GBMs compared to lower grade astrocytomas, indicating FABP7 as a potential GSC biomarker." (PMID 31752169, 2019). "As reported 40-42, the expression levels of Nanog (paired Student's t-test), Sox2 and CD133 were significantly increased in glioma tissues compared with those in normal brain tissues, and their levels were especially increased in high-grade glioma tissues." (PMID 31534499, 2019). "Moreover, AP-2α expression was negatively correlated with the expression of Nanog (Pearson correlation coefficient, -0.3963, P=0.0008), Sox2 and CD133 (Pearson correlation coefficient, -0.4870 and -0.4714, P<0.001) in glioma samples." (PMID 31534499, 2019). "In a glioma model, FASN expression and lipid synthesis were high in patient-derived TICs, along with glioma TIC markers SOX2, fatty acid binding protein-2 (FABP2) and nestin, and FASN inhibition led to downregulation of these markers as well as decreased viability and invasivity." (PMID 31661927, 2019). "Quantitative RT-PCR analysis showed decreased expression of Nanog, Sox2, KLF4, nestin and CD133, together with increased expression of the differentiation marker glial fibrillary acidic protein (GFAP) in AP-2α overexpressing glioma cells." (PMID 31534499, 2019). "Glioma CSCs can produce PEDF and engage in their own autocrine regulation of self-stemness/-renewal, which occurs by activation of EGFRvIII/STAT3/PEDF or Notch/Sox2 signaling." (PMID 30510501, 2018). "This asymmetry in glioma CSCs is ensured by different distribution of the GFR (EGFR) molecules, transcription factors (e.g., Oct4, Sox2, etc.), membrane glycoproteins and proteoglycans (CD133, NG2) regulating stem cell properties and suppressing differentiation." (PMID 30510501, 2018). "Consequently, SOX2 mediated the METTL3-dependent maintenance and radioresistance of glioma stem-like cells." (PMID 30149601, 2018). "Interestingly, MELK activity together with FOXM1 has been shown to positively regulate both SOX2 and EZH2 in other tumours, such as glioma and medulloblastoma." (PMID 29437778, 2018). "Furthermore, the loss of function assay revealed that knockdown of lncTCF7 significantly inhibited glioma cell migration, proliferation and tumorigenicity through upregulating E-cadherin or suppressing TCF7/Sox2 and CyclinD1 expression." (PMID 29234033, 2017). "To validate whether inhibition of CMV70-3P decreases SOX2 protein expression, we used GBM13 patient-derived glioma cells (CMV positive) and U118 cells infected with CMV and then transduced with CMV70-3P or NCmiRNA." (PMID 27517625, 2017). "Furthermore glial tumor markers such as OLIG2 and GLI1 and GSC markers such as MSI1 and SOX2 were also significantly reduced in F3.EGFRviii spheres." (PMID 28830458, 2017).